HRH2 (histamine receptor H2)
Description:
G protein-coupled receptor for histamine, primarily mediating gastric acid secretion. Predominantly expressed in the gastric mucosa, couples to G(s) G alpha proteins upon histamine binding, leading to activation of adenylate cyclase and increased intracellular cyclic AMP (cAMP) levels. This signaling cascade stimulates parietal cells to secrete hydrochloric acid, playing a key role in digestive physiology. Also expressed in other tissues, including the heart and central nervous system, where it may contribute to cardiac stimulation and modulate neurotransmitter release (By similarity).
Synonyms: H2R; HH2R
Tractability: Small molecule: an approved drug acts on it; a structure with a bound ligand is known; a high-quality ligand is known; it belongs to a druggable protein family. Antibody: its Gene Ontology location is reachable by antibodies, with high confidence; UniProt places it where antibodies can reach, with medium confidence; UniProt predicts a signal peptide or a membrane-spanning region. PROTAC: a small molecule that binds it is known.
Target class: Family A G protein-coupled receptor; Small molecule receptor (family A GPCR); Histamine receptor; Membrane receptor; Monoamine receptor
Chemical probes: TIOTIDINE (high quality)
Safety:
Unwanted effects reported when the protein is acted on. In parentheses: how it was acted on, where the effect was seen, and who reports it.
decreased gastric acid secretion (Lynch et al. (2017): inhibition, acute dosing, immune, cardiovascular, gastrointestinal; Bowes et al. (2012): inhibition, cardiovascular system, gastrointestinal)
emesis (activation; cardiovascular system, gastrointestinal; sources: Urban et al. (2012), Bowes et al. (2012))
increased gastric acid secretion (Lynch et al. (2017): activation, acute dosing, immune, cardiovascular, gastrointestinal; Bowes et al. (2012): activation, cardiovascular system, gastrointestinal)
decreased blood pressure (activation, acute dosing; immune, cardiovascular, gastrointestinal; source: Lynch et al. (2017))
decreased eating (inhibition, acute dosing; immune, cardiovascular, gastrointestinal; source: Lynch et al. (2017))
decreased gastric emptying (inhibition, acute dosing; immune, cardiovascular, gastrointestinal; source: Lynch et al. (2017))
decreased inflammation (inhibition, acute dosing; immune, cardiovascular, gastrointestinal; source: Lynch et al. (2017))
decreased pain (inhibition, acute dosing; immune, cardiovascular, gastrointestinal; source: Lynch et al. (2017))
Decreased, survival (inhibition; source: AOP-Wiki)
increased drinking (activation, acute dosing; immune, cardiovascular, gastrointestinal; source: Lynch et al. (2017))
increased gastric emptying (activation, acute dosing; immune, cardiovascular, gastrointestinal; source: Lynch et al. (2017))
increased heart rate (activation, acute dosing; immune, cardiovascular, gastrointestinal; source: Lynch et al. (2017))
Increased, predation (inhibition; source: AOP-Wiki)
inflammation (activation, acute dosing; immune, cardiovascular, gastrointestinal; source: Lynch et al. (2017))
positive inotropic effect on the human ventricle (activation; cardiovascular system, gastrointestinal; source: Urban et al. (2012))
positive inotropy (activation; cardiovascular system, gastrointestinal; source: Bowes et al. (2012))
reduction of gastric acid secretion (inhibition; cardiovascular system, gastrointestinal; source: Urban et al. (2012))
stimulation of gastric acid secretion (activation; cardiovascular system, gastrointestinal; source: Urban et al. (2012))
Gene: Protein-coding gene on chromosome 5 (175,657,797 to 175,710,756, forward strand). Ensembl gene ENSG00000113749.
Subcellular location: Cell membrane
Pathways (Reactome):
Signal Transduction: G alpha (s) signalling events; Histamine receptors
Gene Ontology:
Molecular function: histamine receptor activity; protein binding; neurotransmitter receptor activity; G protein-coupled receptor activity
Biological process: adenylate cyclase-activating G protein-coupled receptor signaling pathway; chemical synaptic transmission; G protein-coupled receptor signaling pathway, coupled to cyclic nucleotide second messenger; immune response; G protein-coupled receptor signaling pathway; gastric acid secretion; positive regulation of vasoconstriction
Cellular component: dendrite; plasma membrane; membrane; synapse
Genetic constraint (gnomAD): Loss-of-function variants: 4 observed, 21.37 expected, observed/expected ratio (o/e) 0.19, 90% interval 0.091 to 0.43. The upper end of that interval is the gene's LOEUF score, 0.43, which puts it in group 1 of 6, group 1 being the genes least tolerant of losing a copy. Missense variants: 250 observed, 486.16 expected, observed/expected ratio (o/e) 0.51, 90% interval 0.46 to 0.57. Synonymous variants: 197 observed, 211.23 expected, observed/expected ratio (o/e) 0.93, 90% interval 0.83 to 1.05.
Homologues: Orthologues: chimpanzee HRH2 (98% identical), macaque HRH2 (97% identical), dog HRH2 (86% identical), mouse Hrh2 (83% identical), guinea pig HRH2 (82% identical), pig HRH2 (82% identical), rabbit HRH2 (81% identical), rat Hrh2 (76% identical), tropical clawed frog hrh2 (49% identical), zebrafish hrh2a (33% identical). Paralogues in human: HTR4 (30% identical), DRD1 (26% identical), HTR1A (26% identical), DRD5 (26% identical), DRD3 (26% identical), HTR1D (25% identical), DRD4 (24% identical), TAAR6 (24% identical), TAAR9 (23% identical), CHRM5 (23% identical), TAAR1 (23% identical), TAAR5 (23% identical), and 13 more.